CAV1 (caveolin 1)
Diseases named in the same sentence as CAV1 in open-access papers (continued):
Sharing a sentence is not in itself a finding about the gene and the disease.
cancer (continued). "In contrast, Cav1 is overexpressed in certain aggressive cancers, such as prostate, bladder, liver, and pancreatic cancers, where it plays an oncogenic role." (PMID 40963741, 2025). "Cav-1 has been reported to have complex effects on cancer cell migration and invasion, with both pro- and anti-migratory functions reported in different cancer types." (PMID 39833546, 2025). "The silence of caveolin-1 (Cav-1), the primary constituent of membrane caveolae, reproduced the morphological evolutionary behaviour of cancer cells, which is similar to the epithelial-mesenchymal transition process." (PMID 41164943, 2025). "The intricate role of Cav1 in EV dynamics represents a fertile ground for advancing our understanding of cellular communication in cancer." (PMID 40963741, 2025). "Cav1 has emerged as a key regulator of EV biogenesis, cargo sorting, and uptake, with profound implications for cancer progression, metastasis, and therapeutic resistance." (PMID 40963741, 2025). "The presence of Cav1 in TEVs not only serves as a potential biomarker for cancer progression but also actively promotes malignancy by facilitating the acquisition of cancerous traits in recipient cells." (PMID 40963741, 2025). "Among the prominent genes in the ERAD pathway, Ufd1 and Cav1 genes were found to be highly expressed in the cancer group (G2) compared to the (G1) healthy control group (G2 vs. G1), while they were low expressed in all treatment groups (G3, 4 and 5)." (PMID 40579643, 2025). "Consistent with our observations, a recent study showed that CAV1 promotes cancer cell survival in the fatty-acid-rich microenvironment of NAFLD, suggesting CAV1 also aids the adaptation of non-cancerous cells in such environments." (PMID 40715090, 2025). "In the broader context of TEV’s role in cancer progression, caveolin-1 (Cav1) the primary component of caveolae, has emerged as a key focus of interest." (PMID 40963741, 2025). "Increased Cav1 expression in certain cancers inhibits pro-apoptotic proteins such as BAX while increasing anti-apoptotic proteins like Bcl-2, thereby promoting cell survival." (PMID 40963741, 2025). "This phenomenon is critical in radiotherapy for cancer since such overexpression of CAV1 in tumor cells will make them more resistant to radiation." (PMID 41516288, 2025). "In advanced-stage cancers, Cav1 promotes EMT by upregulating mesenchymal markers such as vimentin and N-cadherin while reducing epithelial markers like E-cadherin." (PMID 40963741, 2025). "Our findings reveal, CAV1 knockdown led to a reduction in expression of E-cadherin and p21, increased ki67 positivity, and enhanced cancer stemness markers, alongside diminished AMPKα signalling." (PMID 40715090, 2025). "In contrast, overexpression of Kv1.5 alone does not markedly influence cell viability, highlighting a potential regulatory role of Cav-1 in ion channel-mediated mechanisms that promote cancer cell survival." (PMID 40358155, 2025). "In cancer biology, CAV1 can function as both a tumor suppressor and a promoter depending on cancer type and stage." (PMID 40332409, 2025). "This efficient uptake into cancer cells is likely facilitated by a high expression of Caveolin 1, suggesting the potential involvement of caveolins in the internalization process." (PMID 40006633, 2025). "Given CAV1’s role as a mechanosensor in epithelial cells, its contribution to cancer cell stemness and its promotion of HCC metastasis via autophagy inhibition, we investigated its impact on TKI resistance and EMT." (PMID 40715090, 2025). "Colocalization of Ago2 and CAV1 increases in A549 cancer cells and deletion of CBM of Ago2 decreases the colocalization of Ago2 and CAV1 in the cancer cells." (PMID 38649663, 2024). "Blockage of Ago2/CAV1 interaction with Ago2 K212 substitution with alanine, which mimics K212 acetylation, reduced the invasion and tumorsphere formation of cancer cells." (PMID 38649663, 2024).
cancer (continued). "These expression patterns of caveolin-1 are closely related to cancer progression, metastasis, and drug resistance." (PMID 38172597, 2024). "Corresponding with the increased CAV1 distribution in the plasma membrane fractions, increased Ago2 proteins were detected in the plasma membrane fractions of cancer cells (PM)." (PMID 38649663, 2024). "Src-mediated phosphorylation of Cav1 on tyrosine-14 activates a variety of pathways related to cancer aggressiveness, influencing cell migration, invasion, and resistance to oxidative stress." (PMID 38473215, 2024). "The CAV1-induced metabolic reprogramming of cancer cells, by increasing their glycolytic rate, was also associated with migration and invasion." (PMID 39339236, 2024). "Currently, several studies have shown that the overexpression of CAV-1 is related to cancer progression, angiogenesis and metastasis." (PMID 38298655, 2024). "The levels of Ago2 overlapping with CAV1 in A549 cancer cells (arrowheads) were higher than that of BEAS-2B normal lung epithelial cells (Di)." (PMID 38649663, 2024). "With this interaction in cancer cells, CAV1 sequesters Ago2 on the plasma membranes of cancer cells and regulates the process of selective Ago2/miRNA-mediated translational repression in a compartment-dependent manner." (PMID 38649663, 2024). "Ago2/CAV1 interaction acts as a secondary event in miRNA-mediated suppression and increases the complexity of miRNA actions in cancer." (PMID 38649663, 2024). "Since EMT in cancer cells contributes to drug resistance, stemness, and invasiveness of cancer cells, we examined the effects of Ago2/CAV1 interaction on these cancer cell properties." (PMID 38649663, 2024). "In cancer cells treated with P2 peptides, Ago2 was disassociated from CAV1 on the plasma membranes, but Ago2 was still co-located with CAV1 on the plasma membrane of P2S-treated cancer cells." (PMID 38649663, 2024). "Membrane lysis with RIPA buffer was also required for the complete digestion of EV-associated Ago2 and CAV1 by protease K (Fig. EV5D), indicating the presence of both Ago2 and CAV1 proteins in the cancer cell-derived EVs." (PMID 38649663, 2024). "This process supports increased synthesis of glycosphingolipids that are subsequently secreted in particles that contain both Cav-1 and mitochondrial components, preventing the buildup of damaged mitochondria and subsequent cancer cell death." (PMID 39522029, 2024). "Because Ago2/CAV1 interaction regulates the distribution of Ago2 in intracellular compartments of cancer cells in culture, we examined the effects of this interaction on the distribution of Ago2 in tumors in vivo." (PMID 38649663, 2024). "And Cav-1 downregulation can suppress cancer cells muscle invasion through the inhibition of YAP-dependent mechanotransduction." (PMID 39318372, 2024). "Our current findings provide further validation of the functional importance of Cav-1 and lipid rafts in cancer metastasis." (PMID 39244591, 2024). "Among all of these, MMP2, MMP9, FN1, CD44, SERPINE1, and CAV1 are the most famous collaborators with PLAUR in the cell migration of multiple cancer types." (PMID 38396677, 2024). "Caveolin-1, located in MAMs, is involved in cholesterol efflux, and its overexpression has been identified in a variety of cancers, such as lung, liver, kidney, and colon cancers." (PMID 38172597, 2024). "We show here that a positive charge of Ago2 K212, that is preserved by SIR2-mediated Ago2 deacetylation in cancer cells, is responsible for the direct interaction between Ago2 and Caveolin-1 (CAV1)." (PMID 38649663, 2024). "In this study, we identified the relationship between this unique Ago2/CAV1 interaction, Ago2 subcellular location, and cancer cell behavior." (PMID 38649663, 2024). "The effects of Ago2/CAV1 interaction on a target gene involved in regulating cancer cell behavior, namely the suppression of cancer cell invasion (SCAI), were then examined." (PMID 38649663, 2024).
cancer (continued). "The results indicated that blockage of Ago2/CAV1 interaction in A549 cancer cells with P2 peptides decreased cell viability under paclitaxel (Pac) and gefitinib (Gef) treatment, thereby attenuating drug resistance." (PMID 38649663, 2024). "Blocking Ago2/CAV1 interaction with P2 peptides suppressed the expression of certain miRNAs, including miRNA-3613-3p, in the cancer cells." (PMID 38649663, 2024). "To determine the role of Ago2/CAV1 interaction in Ago2 function, we used miRNA arrays to examine the levels of miRNA in cancer cells in which Ago2/CAV1 interaction was inhibited by P2 or P2S peptides." (PMID 38649663, 2024). "Cav1, known to be suppressed in a variety of cancer cells and oncogene-transformed cells, controls the mechanical phenotype." (PMID 38397421, 2024). "CAV1 also plays a vital role in the progression of various diseases, including cancer, through specific amino acid phosphorylation and regulation of other molecular expressions." (PMID 39494337, 2024). "By interacting with CAV1, this pool regulates the selective miRNA-mediated translational repression of genes involved in cancer development in a compartment-dependent manner." (PMID 38649663, 2024). "The co-culture of CAFs with MDA-MB-231 decreased caveolin-1 (CAV-1) expression associated with oxidative stress, which is one of the hallmarks of cancer." (PMID 38455762, 2024). "MicroRNA-3613-3p-mediated suppression of SCAI depends on the secondary event, Ago2/CAV1 interaction, and contributes to the aggressive phenotypes of cancer cells." (PMID 38649663, 2024). "Only miRNA-3613-3p and miRNA-877-5p were altered with Ago2/CAV1 interaction in both cancer cells and plasma EV of cancer cell-bearing mice (Blue)." (PMID 38649663, 2024). "Recent studies have demonstrated the significant involvement of CAV-1 in cancer development and progression." (PMID 38298655, 2024). "Studies on cancer cells with high CAV1 expression have shown that the expression of NOX1 and ACSL4 is increased, and the expression of FTH1 and GPX4 is decreased, which reduces sensitivity to ferroptosis." (PMID 38313306, 2024). "Blocking Ago2/CAV1 interaction in cancer cells decreased lung targeting of circulating cancer cells." (PMID 38649663, 2024). "When cancer cells were subjected to tensile forces that provided by parallel-arranged nanofibers, increased Cav-1 expression induced actin polymerization, promoted the nuclear translocation of YAP and FAs assemble, and enhanced directional migration." (PMID 39318372, 2024). "Many of these Ago2/CAV1-dependent aggressive phenotypes of cancer cells (i.e., invasion, metastasis, EMT, drug resistance, and stemness, are associated with miR-3613-3p-mediated suppression of SCAI." (PMID 38649663, 2024). "Rectangular shaped cancer cells showed stress fibers through the long axis, while Cav-1 silenced cells exhibited significant impaired stress fibers formation." (PMID 39318372, 2024). "Blockage of Ago2/CAV1 interaction in A549 cancer cells with P2 peptides also made the cells sensitive to anoikis, which is a hallmark of EMT." (PMID 38649663, 2024). "•Downregulation of Cav-1 suppresses muscle invasion of cancer cells induced by isotropic ECM fibers." (PMID 39318372, 2024). "Disruption of Ago2/CAV1 interaction by P2 peptides resulted in fluctuations in different miRNAs in cancer cells." (PMID 38649663, 2024). "Collectively, these insights underscore Cav-1’s multifaceted involvement in the promotion of metastasis in different types of cancers." (PMID 39244591, 2024). "In silico modeling and coimmunoprecipitation analysis revealed a possible interaction between Cav-1 and ITGα3, which are both membrane proteins that play crucial roles in cancer progression." (PMID 39244591, 2024). "Caveolin-1 plays an important role in the regulation of cell proliferation, migration and angiogenesis, suggesting a link to cancer development and invasion." (PMID 38542507, 2024).
cancer (continued). "The results suggest that CBM of Ago2 is responsible for the increased colocalization of Ago2 and CAV1 in cancer cells." (PMID 38649663, 2024). "This condition-dependent interaction suggests a regulatory role of Ago2/CAV1 interaction in the distribution and function of Ago2 in carcinoma progression and metastasis." (PMID 38649663, 2024). "Although CAV1 has been known to be upregulated in cancer cells, there are reports that CAV1 is downregulated in lung, breast, colon, and ovarian cancer." (PMID 37919422, 2023). "In such cancer cells, CAV1 promotes β-cat recruitment to the plasma membrane, thereby precluding upregulation of β-cat/Tcf-Lef target genes like survivin and COX-2." (PMID 38069269, 2023). "This contributes to the selective attack of cancer cells with high levels of caveolin-1 and the reduction in unwanted side-effects on normal cells." (PMID 37958616, 2023). "Representative tissue cores for normal and cancer prostate tissue with clathrin (red) and caveolin-1 (green) show an increase in the expression of the former and corresponding decrease of expression of the latter in cancer tissue." (PMID 36869937, 2023). "According to recent reports, both CAV1 and BST2 are highly associated with the cell proliferation and metastasis of different cancers 24-26." (PMID 36594082, 2023). "Studies from our group have shown that treatment of cancer cells with PGE2 promotes the liberation of β-cat from the multiprotein complex that it forms with CAV1/E-cad." (PMID 38069269, 2023). "CAV1 also contributes to glioma cancer stemness, cancer cell invasion, immune infiltration and cancer cells’ resistance to OXPHOS-inhibition drugs." (PMID 37642765, 2023). "Conversely, decreased caveolin-1/DAPI GIC values were found in cancer compared to normal tissue (p = 0.03), indicating a loss of caveolin expression in the nucleus in cancer." (PMID 36869937, 2023). "CAV1 genotyping was done using a SNParray designed to investigate genetic variations in relation to cancer." (PMID 37017811, 2023). "Previous studies indicated that CAV1 is involved in the modulation of cancer metabolism and glycolytic activities." (PMID 37642765, 2023). "The biological context is of great importance as CAV1 can both favor cancer progression and its inhibition due to participation in such processes as apoptosis, invasion, or migration." (PMID 37233761, 2023). "Caveolin-1 is also reduced in other cancers such as those of the breast, liver and ovary [reviewed in]." (PMID 36869937, 2023). "The expression of clathrin is almost exclusively found in epithelial cells in both normal and cancer samples whereas caveolin-1, in addition to being expressed largely in stromal tissue, also shows expression in epithelial cells in normal tissue." (PMID 36869937, 2023). "In breast cancer, CAV1 has been shown to inhibit the growth and metastasis of cancer cells and suppress the self-renewal capacity of cancer stem cells." (PMID 37919422, 2023). "Then we checked the methylation status of CAV1 in cancer and normal samples with the consideration of several factors including gender, pathological stages, copy numbers, etc.." (PMID 37642765, 2023). "The same alterations are shown in the PDAC model, where Cav-1 is lost in response to PSCs activation, correlating with stromal and cancer cells metabolic coupling." (PMID 37033960, 2023). "In some types of cancer, including LC, DNA-methylation represses the CAV1 gene at cancer onset, but demethylation and the concomitant re-expression of this gene occur before metastasis 73-75." (PMID 37928877, 2023). "The ubiquitination of caveolin 1 (CAV1) mediated by zinc and ring finger 1 (ZNRF1) is blocked by circFARP1, thus leading to the release of leukemia inhibitory factor (LIF1) in cancer-associated fibroblasts (CAFs) and eventually promoting GEM resistance." (PMID 38174069, 2023).
cancer (continued). "Perex exhibited potent anti-cancer activities, inhibiting the proliferation, migration, and invasion of MDA-MB-231 cancer cells, which have high levels of caveolin-1 compared to other cancer and normal cells." (PMID 37958616, 2023). "This selective attack on cancer cells with high levels of caveolin-1 reduces unwanted side-effects on normal cells." (PMID 37958616, 2023). "Cav-2 also has dual functions of inhibiting and promoting cancer and can be expressed in combination with Cav-1 or play a regulatory role alone." (PMID 37828916, 2023). "With regard to the potential mechanism, an increasing number of evidence showed that CAV-1 is closely related to the redox signal of cancer cells." (PMID 36874003, 2023). "Our earlier work identified CAV1 as a potent negative regulator of genes whose expression favors the development and progression of cancer." (PMID 38069269, 2023). "The role of CAV1 in cancer drug resistance was broadly explored, however more knowledge is required to exploit this concept in the clinical setting." (PMID 35158857, 2022). "In this study, we show that the expression of CAV1 promotes in cancer cells a metabolic switch to an aerobic, glycolytic phenotype by blocking mitochondrial respiration." (PMID 35740528, 2022). "Consistently, the protein levels of pSTAT3, SOX2, CDA, and ABCC2 in cancer cells were decreased after silencing CAV1 in CAFs." (PMID 35045883, 2022). "To test Trastzumab binding in HER2+ cancer cells expressing varying levels of CAV1, we first used a panel of GC cell lines: the HER2+ GC cell line (WT, NCIN87) and three GC cell lines (AGS, KATOIII, and SNU1) stably expressing HER2 (LV-HER2)." (PMID 35534471, 2022). "In conclusion, our results demonstrate that CAV1 participates in the metabolic reprogramming of cancer cells by controlling the mitochondrial oxidative phosphorylation pathway." (PMID 35740528, 2022). "Particularly, activated fibroblasts, also termed cancer-associated fibroblasts (CAF), were shown to foster therapy resistance of malignant epithelial cells in a CAV1-dependent manner." (PMID 35155239, 2022). "Caveolin-1 (CAV-1) is a scaffold protein of caveolae that is related to the proliferation and metabolism of cancer cells." (PMID 36604141, 2022). "The restoration of Cav1 suppressed cell proliferation in benign tumor cells, and is a tumor suppressor in the early stage of cancer." (PMID 35625714, 2022). "In contrast, knockdown of CAV1 sensitized pancreas-cancer cells to ionizing radiation concomitant with reduced expression of β1-integrin and Akt phosphorylation and activation of apoptosis by caspase-3 and caspase-8." (PMID 35158857, 2022). "In contrast, in cancer cell lines, Src-mediated phosphorylation of CAV1 has been described to promote P-gp translocation to the caveolae and induce multidrug resistance." (PMID 35158857, 2022). "Previous reports showed that CAV1 depletion down-regulated lactate accumulation in human colon and prostate cancer cell lines." (PMID 35740528, 2022). "Next, we explored the mechanism by which the NS1643-induced dephosphorylation of Cav-1 inhibits cancer cell migration." (PMID 35954304, 2022). "Considering the lower Cav1 expression in several cancers, these data highlight the role of tumor suppressor Cav1 in the initiation of tumorigenesis." (PMID 35625714, 2022). "Cav1 is an important factor involved in tumorigenesis and progression of many cancers, and Cav1 can regulate fatty acid metabolism by activating SREBP-1, thereby inhibiting ACADM in HCC." (PMID 35743814, 2022). "Taken together, these studies indicate that the Kv11.1 activation-dependent dephosphorylation of Cav-1 arrests cancer cell migration, and thereby substantiates its potential clinical use for the prevention of metastasis." (PMID 35954304, 2022). "Cav-1-rich CAFs regulate Rho-mediated cell contractility in a p190-dependent manner and promote the local invasiveness and metastasis of cancer cells by remodeling the ECM." (PMID 36422541, 2022).